LINC01232 (long independently transcribed non-coding RNA 1232)
Synonyms: FLJ41590; TCONS_00021520; formerly LINC00449
Gene: Long non-coding RNA gene on chromosome 13 (99,479,448 to 99,501,342, reverse strand). Ensembl gene ENSG00000280734.
Diseases named in the same sentence as LINC01232 in open-access papers:
LINC01232 is named in the same sentence as 16 diseases in open-access papers, as found by Europe PMC text mining. Sharing a sentence is not in itself a finding about the gene and the disease. The quoted sentences say what the papers report.
pancreatic cancer (7 papers, 2019 to 2023). "In pancreatic cancer, hnRNPA2B1 interacts with linc01232 to accelerate metastasis through A-Raf-induced MAPK/ERK signaling pathway activation." (PMID 35279145, 2022). "Among the ones that have been reported, LINC01232 promotes metastasis and participates in the progression of pancreatic cancer." (PMID 35144613, 2022). "In conclusion, this study was the first to unveil the role and molecular mechanism of LINC01232, suggesting LINC01232 as a promising molecular target for pancreatic cancer treatment." (PMID 31541081, 2019). "In pancreatic cancer, LINC01232 modulates TM9SF2 mRNA stability via recruiting EIF4A3." (PMID 37940881, 2023). "Rescue experiments were performed to explore whether LINC01232 affected the tumorigenesis and development of pancreatic cancer by TM9SF2." (PMID 31541081, 2019). "Besides, LINC01232 has been found to be involved in other cancers, such as PAAD, pancreatic cancer (PC) and ESCC." (PMID 34783622, 2021).
pancreatic adenocarcinoma (3 papers, 2019 to 2021). "Another study found that EIF4A3 is recruited by LINC01232 to stabilize transmembrane 9 superfamily member 2 (TM9SF2) mRNA and regulate its expression, thereby contributing to pancreatic adenocarcinoma (PAAD)." (PMID 34458150, 2021).
clear cell renal cell carcinoma (2 papers, 2021 to 2022). "Professor Liu confirmed that LINC01232 promotes clear cell renal cell carcinoma by binding miR-204-5p to upregulate RAB22A." (PMID 35910212, 2022).
colon adenocarcinoma (2 papers, 2021 to 2023). "LncRNAs play crucial roles in the progression of colon adenocarcinoma (COAD), but the role of LINC01232 in COAD has not received much attention." (PMID 36655275, 2023).
gastric cancer (2 papers, 2021 to 2024). A primary or metastatic malignant neoplasm involving the stomach. "The knockdown of LINC01232 is shown to suppress the proliferation of gastric-cancer cells both in vivo and in vitro." (PMID 38542354, 2024). "Rescue experiments were further conducted to elucidate the biological function of LINC01232/KLF2 axis in the progression of gastric cancer." (PMID 34409953, 2021). "LncATLAS database and subcellular isolation assay were used for subcellular distribution of LINC01232 in gastric cancer cells." (PMID 34409953, 2021). "The results revealed that the expression of LINC01232 mRNA in gastric cancer cells was significantly higher than that in human gastric mucosal cell GES-1 (p < 0.05, respectively)." (PMID 34409953, 2021). "In conclusion, our study showed that LINC01232 exerts oncogenic activities in gastric cancer and LINC01232 knockdown could inhibit the proliferation of gastric cancer cells in vivo and in vitro." (PMID 34409953, 2021). "The regulation of LINC01232 may be an effective potential therapeutic and preventive approach for gastric cancer." (PMID 34409953, 2021). "We conducted rescue experiments to further clarify the functions of LINC01232 and KLF2 in the progression of gastric cancer." (PMID 34409953, 2021). "In this study, we found that the expression of LINC01232 was upregulated in STAD tissues and gastric cancer lines, indicating that LINC01232 may be a functional gene and a molecular target for clinical treatment of gastric cancer." (PMID 34409953, 2021). "LINC01232 exerts oncogenic activities in gastric cancer via inhibition of KLF2, and therefore, the knockdown of KLF2 could reverse the regulatory effect of LINC01232 in the proliferative ability of gastric cancer cells." (PMID 34409953, 2021).
colon cancer (1 paper, 2023). "Thus, LINC01232 has been confirmed to be implicated in the progression of colon cancer in our study." (PMID 36655275, 2023).
glioma (1 paper, 2023). A benign or malignant brain and spinal cord tumor that arises from glial cells (astrocytes, oligodendrocytes, ependymal cells). "To verify that LINC01232 promotes glioma immune escape by regulating NBR1, we knocked down NBR1 in the glioma cell lines U‐87MG and U‐251 while overexpressing LINC01232." (PMID 37097629, 2023). "Based on these results, LINC01232 appears to be contained in M2‐secreted exosomes and may be capable of being transferred to glioma cells." (PMID 37097629, 2023). "This study reveals the existence of critical molecular crosstalk between TAMs and glioma mediates through the LINC01232/E2F2/NBR1/MHC‐I axis to support malignant tumor growth, indicating that targeting this axis may have therapeutic potential." (PMID 37097629, 2023). "In addition, we examined the correlation between LINC01232 mRNA levels and the clinicopathological characteristics of 80 glioma specimens." (PMID 37097629, 2023). "Moreover, the subcellular location of LINC01232 was investigated by FISH and subcellular fractionation, and the results showed that LINC01232 localized in both the nucleus and cytoplasm, and mainly in the nuclei of glioma cells." (PMID 37097629, 2023). "In addition, blocking the synthesis of exosomes or knocking down LINC01232 expression can attenuate the ability of M2‐TAMs to induce glioma immune escape." (PMID 37097629, 2023). "The LINC01232/E2F2/NBR1/MHC‐I expression levels among normal brain tissues (NBT), low‐grade glioma tissues (LGG), and high‐grade glioma tissues (HGG) were compared." (PMID 37097629, 2023). "We found that LINC01232 was highly expressed in M2‐TAM‐derived exosomes, and functional experiments confirmed that exosomes‐LINC01232 derived from M2‐TAMs promoted the immune escape of glioma cells by evading CD8+ CTL cells." (PMID 37097629, 2023). "Flow cytometry and real‐time quantitative PCR results indicated that CD8+ T cells cocultured with LINC01232‐OE glioma cells showed lower proliferation and expression of IFN‐γ, TNF‐α, and Gzmb; however, knocking down NBR1 while overexpressing LINC01232 could reverse this phenomenon." (PMID 37097629, 2023).
tumor (6 papers, 2021 to 2025). "The tumor-associated macrophage-derived exosomal long intergenic noncoding RNA (ncRNA) LINC01232 induces immune escape in glioma by downregulating tumor MHC-I." (PMID 40659888, 2025). "In this study, we found that TAMs secrete exosomes rich in LINC01232 into tumor cells and that LINC01232 directly binds E2F2 and promotes E2F2 entry into the nucleus; the two synergistically promote the transcription of NBR1." (PMID 37097629, 2023). "Disruption of LINC01232/E2F2/NBR1/MHC‐I by shRNA or blocking the corresponding antibodies largely diminished the tumor‐supportive effects of LINC01232 and suppressed tumor growth driven by M2‐type macrophages." (PMID 37097629, 2023). "In our study cohort, we also found a markedly higher level of LINC01232 in ccRCC tumour tissues and cell lines, and LINC01232 was markedly correlated with tumour size, lymph node metastasis and TNM stage." (PMID 34783622, 2021). "LINC01232 expression was increased in ccRCC tumour tissues and ccRCC cells and independently predicted the prognosis of ccRCC patients." (PMID 34783622, 2021). "In this study, by using a bioinformatics analysis platform, we found that the expression levels of LINC01232 in ccRCC tumour tissues were significantly upregulated and significantly correlated with disease prognosis." (PMID 34783622, 2021). "TAMs secrete exosomal LINC01232, which promotes immune evasion by tumor cells." (PMID 41502528, 2025). "Importantly, knockdown of LINC01232 enhanced MHC‐I expression on the tumor cell surface, whereas overexpression of LINC01232 attenuated MHC‐I expression." (PMID 37097629, 2023). "The results of IF analysis of Ki‐67 in the transplanted tumor specimens from the animals indicated that mice in the sh‐1232#1 group expressed less Ki‐67 than mice in the sh‐NC group; next, LINC01232 knockdown and simultaneous overexpression of NBR1 could reverse this phenomenon." (PMID 37097629, 2023). "The IF results of Ki‐67 in the transplanted tumor specimens from the animals indicated that mice in the LINC01232‐OE group had increased expression of Ki‐67 compared with the mice in the vector group; next, NBR1 knockdown with simultaneous overexpression of LINC01232 could reverse this phenomenon." (PMID 37097629, 2023). "Therefore, the purpose of this study was to analyse the expression level of LINC01232 in ccRCC tumour tissues and ccRCC cell lines, explore the role of LINC01232 in ccRCC tumour progression using in vitro experiments, and provide a preliminary exploration of its molecular mechanisms." (PMID 34783622, 2021). "Thus, LINC01232 may function as a tumour promotor in ccRCC progression and pathogenesis." (PMID 34783622, 2021). "In addition, LINC01232 facilitates ccRCC tumour progression via sponging miR-204-5p and increasing RAB22A, suggesting the critical role of the LINC01232/miR-204-5p/RAB22A axis in ccRCC progression." (PMID 34783622, 2021). "LINC01232 binds to E2F2 to enter the nucleus and collaboratively upregulates NBR1, mediating the degradation of histocompatibility complex Class I molecules (MHC-I) by autophagy lysosomes, enabling CD8+ T cells to effectively recognize tumor-specific antigens and thereby evade immune surveillance." (PMID 40585979, 2025). "Interestingly, the results of cell coculture showed that LINC01232‐OE/U‐87MG/U‐251 cells significantly inhibited T‐cell‐mediated tumor cell killing compared with vector; however, knocking down NBR1 while overexpressing LINC01232 could reverse this phenomenon." (PMID 37097629, 2023). "The IHC results of CD8+ in animal transplanted tumor specimens demonstrated that, compared with mice in the vector group, those in the LINC01232‐OE group had significantly lower expression of CD8+; next, NBR1 knockdown with simultaneous LINC01232 overexpression could reverse this phenomenon." (PMID 37097629, 2023).
cancer (3 papers, 2021 to 2023). A tumor composed of atypical neoplastic, often pleomorphic cells that invade other tissues. "In addition, the expression of LINC01232 in other types of cancer was also assessed using the TCGA dataset." (PMID 34783622, 2021).
LINC01232 also shares sentences with these, for which no sentence is quoted: acute myeloid leukemia (1 paper); hepatocellular carcinoma (1); lung squamous cell carcinoma (1); oral carcinoma (1); prostate adenocarcinoma (1); Stomach Adenocarcinoma (1); triple-negative breast carcinoma (1).